TRPV1 (transient receptor potential cation channel subfamily V member 1)
Diseases named in the same sentence as TRPV1 in open-access papers (continued):
Sharing a sentence is not in itself a finding about the gene and the disease.
cancer (continued). "A phase III study (NCT04572776) is currently investigating the role of TRPV1 in intractable cancer pain through a single epidural administration of resiniferatoxin vs. the standard of care." (PMID 37892239, 2023). "Such nanoparticles-mediated TRPV1 blockade provides an emerging paradigm to dismantle self-defenses of tumors for safely amplifying cancer therapy against highly intractable tumors." (PMID 37120615, 2023). "TRPV1 activation was found to be involved in the induction of cell death in different cancer models including bladder cancer, glioma, human gastric cancer, and breast cancer." (PMID 36876044, 2023). "Three large epidemiological studies suggest that TRPV1 activation by culinary capsaicin exposure protects against cancer." (PMID 37371563, 2023). "TRPV1 channels have recently been found to play an important role in cancer development and tumorigenesis, in various types of cancer." (PMID 38328578, 2023). "Here, we review the neuro-immune modulation of cancer growth and metastasis, with focus on the consequences of TRPV1 activation in nerve fibers and immune cells." (PMID 37371563, 2023). "TRPV1 blockade was identified to induce the enhanced cancer thermotherapy by the combination of intratumoral TRPV1 antagonist (SB705498) with CuS-NCs-triggered hyperthermia." (PMID 37120615, 2023). "We next determined the mechanism of the regulation of osteolytic cancer cells progression in tibiae and lung metastasis from tibiae following TRPV1 activation." (PMID 37461623, 2023). "It has been reported that in many cancers, capsaicin displays proapoptotic activity promoted by the TRPV1 (transient receptor potential vanilloid type-1) channel." (PMID 37507999, 2023). "The nanoparticle-mediated TRPV1 blockade represents as an effective approach to dismantle self-defenses for potent cancer therapy." (PMID 37120615, 2023). "According to studies, the activation of TRPV1 induced by capsaicin has been shown to inhibit cancer cell growth through apoptosis." (PMID 37189782, 2023). "The results presented so far sustain the role of TRPA1 and TRPV1 in cancer cell proliferation but are irrelevant to the modulation of channels by ROS." (PMID 37507867, 2023). "In conclusion, there is good evidence to implicate TRPV1-expressing afferents and immune cells in the bi-directional communication between cancer and its microenvironment." (PMID 37371563, 2023). "The ability of capsaicin to modulate the intestinal microbiota has been discussed not only as one of its TRPV1-independent effects but also as the basis for other beneficial systemic effects on metabolic diseases and cancer." (PMID 37892544, 2023). "Several ligands were found to sensitize TRPV1 after the prolonged exposure and cancer chemotherapeutic agents were among the top such TRPV1 sensitizing agents." (PMID 38052846, 2023). "Prominent red fluorescence from TRPV1 channels was observed in different cancer cell lines including HepG2, MAD-MB-231, HCT-116 and PANC1 cancer cells, suggesting that TRPV1 channels are abundantly expressed on these cells." (PMID 37120615, 2023). "For example, TRPV1 expression showed a positive correlation with the ratio of immune-stimulatory over immunosuppressive signatures (CD8+ T cell/PD-L1) in five cancer types." (PMID 37371563, 2023). "Previous studies have shown that activation of the heat-sensing ion channel TRPV1 can suppress the growth of cancer cells in a process known as apoptosis." (PMID 37189782, 2023). "With immunohistochemistry using an anti-TRPV1 antibody (Cell Signaling Technologies, Boston, MA), decreased TRPV1 protein expression was found in cancer biopsies compared to adjacent normal tissue." (PMID 37240443, 2023).
cancer (continued). "Mice lacking Trpv1 are non-responsive to capsaicin, whereas mice with increased expression of Trpv1 due to genetic alterations or cancer show increased sensitivity to capsaicin." (PMID 36368973, 2022). "Kaplan-Meier survival analysis indicated that the hypermethylation of TRPV1 in LAML and BLCA, TRPV4 in SARC and UCEC, TRPV5 in BLCA, TRPV2 in ACC, and SARC cancers was associated with a poor prognosis in most tumors." (PMID 35174089, 2022). "Capsaicin’s anti-cancer effect has been observed through the binding to transient receptor potential cation channel subfamily V member 1 (TRPV1), which leads to an increase in intracellular calcium and thus apoptosis." (PMID 36428575, 2022). "Subcutaneous injection of TRPV1 antagonist JNJ-17203212 alleviated pain behaviors at different stages of cancer progression." (PMID 36438444, 2022). "For example, TRPA1, TRPC1, TRPV4, TRPV5, and TRPV6 exhibited higher CNV amplification, while TRPV1, TRPV2, TRPV3, and TRPC3 exhibited frequent CNV loss in cancer." (PMID 35614079, 2022). "Significantly, capsaicin, a vanilloid and TRPV1 agonist, was found to be cytotoxic to a number of cancer cell lines through both TRPV1-dependent and -independent mechanisms raising the prospect that TRPV1 expression can be exploited therapeutically." (PMID 35477804, 2022). "The transient receptor potential vanilloid (TRPV) channels family, TRPV1-6, has been identified to profoundly affect a wide spectrum of pathological processes in various cancers." (PMID 35558077, 2022). "Preclinical cancer pain models differ in impact of TRPV1 antagonism on mechanical allodynia and thermal hyperalgesia." (PMID 36368973, 2022). "The percent of retrograde labeled TG neurons that respond to TRPV1 agonist, capsaicin, is increased along with the magnitude of response as measured by calcium influx, in neurons from the cancer models." (PMID 35260737, 2022). "Capsaicin (CAP) is known to activate the transient receptor potential cation channel subfamily V member 1 (TRPV1) channels and inhibit cancer growth." (PMID 36187775, 2022). "It has been recently discovered that TRPV1 plays essential roles in cancer tumorigenesis and development." (PMID 35214061, 2022). "Most published data suggests that TRPV1 suppresses EGFR signalling in cancer cells and, therefore, has anti-tumorigenic effects." (PMID 36497413, 2022). "Elevated expression of TRPV1 correlated with better clinical outcomes in pan-cancer and diverse cancer types." (PMID 36304985, 2022). "This study is aimed at furnishing novel insights into the role of TRPV1 in both cancer biology and clinical practice." (PMID 36304985, 2022). "It is generally believed that cancer pain is complex, so the regulation mechanisms of TRPV1 are also complex." (PMID 36438444, 2022). "While afferent neurons throughout the different heterosegmental regions express TRPV1, the oral cavity is an ideal site to study TRPV1 sensitization in the setting of cancer." (PMID 35260737, 2022). "Our analysis showed that TRPV1 expression levels correlated negatively with HRD scores in pan-cancer (p = 1.84 × 10−14; ρ = −0.12)." (PMID 36304985, 2022). "At the same time, a study has found that the mechanism of EA at ST36 acupoint to relieve cancer pain is related to the expression of TRPV1." (PMID 35845135, 2022). "Our analysis showed that TRPV1 expression levels correlated negatively with TMB in pan-cancer (p = 8.92 × 10−51; ρ = −0.23)." (PMID 36304985, 2022). "It was recently revealed that TRPV1 is involved in cancer development and progression, although the precise role that TRPV1 plays remains to be elucidated." (PMID 35214061, 2022). "In the past, different TRPV1 agonists, especially capsaicin, were shown to trigger cell death in TRPV1 expressing cancer cells." (PMID 35458699, 2022). "Further studies have concluded that the concentration of a TRPV1 agonist known as extracellular polyamines in gastrointestinal tissues intensifies during cancer and inflammation." (PMID 36499622, 2022).
cancer (continued). "But few research has elucidated the role of TRPV1 in malignancies, especially the correlations of TRPV1 to the prognoses and tumor‐infiltrating lymphocytes (TILs) in different cancers remain poorly described." (PMID 35620019, 2022). "Subsequently, the CNV percentage analysis in specific cancer subtypes of Hete Amp and Hete Del showed that TRPV1-6 (except for TRPV4) in KIRP, TRPV4 in ACC, TRPV6 and TRPV5 in GBM had greater than 40% Hete Amp levels." (PMID 35174089, 2022). "The targets of evodiamine include topoisomerases, aryl hydrocarbon receptor (AhR), and transient receptor potential cation channel subfamily V member 1 (TRPV1) in the treatment of different types of cancers." (PMID 35899176, 2022). "To fill this research gap, we explored correlations of TRPV1 expression with immune signatures' enrichment, progression phenotypes, and clinical outcomes in ten cancer types from The Cancer Genome Atlas (TCGA) program." (PMID 36304985, 2022). "Our results provide new understanding of the role of TRPV1 in both cancer biology and clinical practice." (PMID 36304985, 2022). "For example, TRPV1 has been extensively studied for its role in regulating the balance between proliferation and apoptosis in various cancer cell lines; however, the evidence for it being pro-apoptotic or pro-proliferative is somewhat inconsistent." (PMID 36497413, 2022). "Among the Transient Receptor Potential (TRP) family, several channels, such as TRP Ankyrin 1 (TRPA1) and Vanilloid 1 (TRPV1), have been suggested to play roles in many cancer types, including breast, digestive, gliomas, lung, prostate and HNSCC." (PMID 35163843, 2022). "Then the correlation between TRPs and hazard ratio (HR) was detected, and found that the TRPV1 was negatively correlated with cancer risk; TRPM1 and TRPM4 were positively correlated with cancer risk." (PMID 36072430, 2022). "Previous studies have shown that TRPV1 can inhibit the development of cancer by regulating the Ca2+/CaMKKβ/AMPK pathway." (PMID 36304985, 2022). "In summary, we elucidated that TRPV1 expression was upregulated in cancer tissue of LUAD patients and significantly negatively correlated to the OS of LUAD patients." (PMID 35620019, 2022). "Some pharmacological regulators activate not only TRPV1 but also other reporters to affect cancer cell proliferation." (PMID 34131404, 2021). "Few published reports describe the direct impact of altering TRPV1 expression on cancer cell metastasis." (PMID 34131404, 2021). "TRPV1 channel activation increases the intracellular Ca2+ concentration, and Ca2+ signaling plays an essential role in cancer cell proliferation, regulation, and survival." (PMID 34131404, 2021). "In the carcinoma cell inoculation model, ST36 EA relieved the cancer-induced pain by suppressing the expression of TRPV1 protein and mRNA in the L3–5 DRG." (PMID 35095910, 2021). "As we mentioned, numerous studies have revealed that TRPV1 agonists/antagonists affect cancer proliferation, cell death, and metastasis by activating TRPV1 channels and subsequently increasing the levels of intracellular Ca2+." (PMID 34131404, 2021). "Baicalin is reported to be compound with a crucial role in the treatment of cancer-induced bone pain, via the upregulation of transient receptor potential vanilloid 1 (TRPV1), thus preventing the progression of bone pain in cancer." (PMID 33748269, 2021). "The authors shed light on the fact that neurons are more sensitive to capsaicin than cancer cells with confirmed TRPV1 expression." (PMID 33804707, 2021). "As mentioned in the previous section, TRPV1 overexpression or agonist treatment induces apoptosis, preventing cancer cell proliferation." (PMID 34131404, 2021). "Recently, calcium signaling was found to be closely related to carcinogenesis and metastasis 104-106, yet only a few reports mention the role of TRPV1 in cancer cell metastasis." (PMID 34131404, 2021).
cancer (continued). "In recent years, TRPV1 was discovered to play essential roles in cancer tumorigenesis and development, as TRPV1 expression levels are altered in numerous cancer cell types." (PMID 34131404, 2021). "TRPV1, through [Ca2+]i signaling, influences cancer cell fate; therefore, the modulation of the TRPV1-enforced proliferation–apoptosis balance is a promising avenue in developing anti-cancer therapies and overcoming cancer drug resistance." (PMID 32545311, 2020). "Capsazepine, a prototype TRPV1 antagonist, reportedly possesses anti-cancer activity and induces endoplasmic reticulum (ER) stress in several cancer cells." (PMID 32604833, 2020). "TRPV1 mRNA and protein are expressed in optic, pulmonary, nervous, cardiac, skeletal, circulatory, and skin cells, as well as in numerous cancer cell lines." (PMID 32545311, 2020). "Targeting of TRPV1 represents an important avenue for cancer management, and current progress in related oncologic strategies is promising." (PMID 32545311, 2020). "Primarily, TRPV1 agonist-induced anti-cancer activities seem to involve TRPV1 and its calcium signaling." (PMID 32604833, 2020). "Although some reports have shown the pro-tumor activity of capsaicin, accumulating evidence indicates that TRPV1 agonists have anti-cancer activities." (PMID 32604833, 2020). "TRPV1 mediates acute as well as chronic pain perception, also elicited by the acidic environment of cancer." (PMID 32887220, 2020). "According to the results from the Oncomine database, the profiles of TRPV1 expression varied in different cancers." (PMID 32913462, 2020). "Further research is necessary to fully elucidate the dependence of TRPV1’s inflammatory effects on agonist type, cell/cancer type, and tumor microenvironment." (PMID 32545311, 2020). "Our results also suggest that SHP-1 in sensory neurons is an endogenous pain inhibitor and delays the development of cancer-induced bone pain via suppressing TRPV1 function." (PMID 32960817, 2020). "TRPV1 has been recognized as an important regulator of intracellular calcium levels and was shown to be functionally expressed in various cancer cells." (PMID 33239060, 2020). "In this study, TRPV1 expression in ccRCC and other cancer types was analyzed based on data from the GEO and Oncomine databases." (PMID 32913462, 2020). "TRPV1 staining has been shown in both normal acini and ducts but with highest intensity in nerves of inflamed tissue surrounding the cancer." (PMID 33178018, 2020). "The linking of TRPV1 and P2Y2 signals to cell proliferation and oncogenicity suggests TRPV1 as a potential target for anti-cancer therapies, in the interest of downregulating proliferative protein signaling." (PMID 32545311, 2020). "Cancer management based on the targeting of TRPV1 currently encompasses a wide range of compounds with synthetic as well as natural origins." (PMID 32545311, 2020). "The TRPV1 channel is highly permeable to calcium ions, which play a critical role in several cellular processes, including apoptosis and proliferation of cancer cells." (PMID 32604833, 2020). "In the development of anti-cancer drugs to affect TRPV1, it is in all cases necessary to first characterize the apoptosis–proliferation balance that exists in the target cell line, taking into account factors such as inflammation." (PMID 32545311, 2020). "Lastly, TRPV1 is already considered as a therapeutic target in cancers because of its involvement in pain sensation." (PMID 32887220, 2020). "The prognostic value of TRPV1 channels in cancer often depends on the cancer type, stage and two-sided nature of [Ca2+]i elevation, which can either induce cancer cell apoptosis or enhance proliferation." (PMID 32887220, 2020). "Alpha-lipoic acid and selenium enhance the cytotoxic efficacy of cisplatin, an existing platinum-derived anti-cancer drug, via TRPV1 stimulation." (PMID 32545311, 2020).
cancer (continued). "In other types of cancers, i.e., gastric and colorectal cancer, astrocytoma and bladder carcinoma, altered TRPV1 expression is also observed, but putative therapeutical benefits of the channel modulation still needs in vivo validation." (PMID 32887220, 2020). "This review aims to characterize the molecular mechanisms through which TRPV1 exerts the mentioned effect in the interest of identifying potential targets for anti-cancer drug development." (PMID 32545311, 2020). "TRPV1 is one of the key receptors mediating the development of pain sensitivity and is also a necessary condition for the occurrence of cancer pain." (PMID 31201657, 2019). "Nerve growth factor (NGF) released by cancer can sensitize sensory nerves and act on TRPV1 (Transient Receptor Potential Vanilloid 1), which in turn correlates with severe pain in patients." (PMID 31248001, 2019). "TP induces the oncogene Pi3 Kinase/Akt which is coupled to the activation of large-conductance potassium calcium channels and Transient Receptor Potential Vanilloid 1 (TRPV1) known to be emerging pharmacological targets in cancer." (PMID 31709268, 2019). "Accumulating evidence suggests a potential role of transient receptor potential vanilloid 1 (TRPV1) channels in inflammatory and cancer-related pain." (PMID 30808963, 2019). "Several studies addressed the TRPV1 activation in anti-cancer therapy via harnessing the Ca2+ signaling." (PMID 31681615, 2019). "Herein, we present a review regarding the role of the TRPV1 channel in the process of inflammation, cancer, and immunity." (PMID 31681615, 2019). "A deeper understanding of TRPV1 channel biology in cancer cell-lines will open opportunities for finding natural products and developing new anti-cancer agents." (PMID 31881661, 2019). "The results confirm the suggestion that TRPV1 activity plays an important role in the SMF enhanced anti-cancer effect." (PMID 29338036, 2018). "In other words, SMF increases the probability of interaction between capsaicin and the transmembrane ion channel TRPV1 and thus enhances the anti-cancer effect exhibited by capsaicin." (PMID 29338036, 2018). "Concerning to cancer pain, a phase I clinical trial is being carried out to determine the efficacy of periganglionic/intrathecal administration of the potent TRPV1 agonist resiniferatoxin in advanced cancer patients with bone pain." (PMID 29491840, 2018). "The TRPV1 activation was confirmed to participate in the synergistic anti-cancer effect by the antagonist experiment and the change of calcium in cytoplasm related to the treatments." (PMID 29338036, 2018). "This modulation of VEGF-induced increases in Ca2+ influx mediated by TRPV1 activation shows that this receptor triad contributes through crosstalk to the growth promoting effects of VEGF in UM cells derived from malignant tumors." (PMID 30483120, 2018). "The result showed that disrupting the function of TRPV1 blocked the enhanced effect of SMF on cancer cell apoptosis." (PMID 29338036, 2018). "Studies had shown that the activation of TRPV1 is capable of inducing apoptosis and inhibiting cancer cell growth by cell cycle arrest in many different types of cancer, while normal cells remained unharmed." (PMID 29338036, 2018). "II) In a previous study we had found that in MCF7 cells merely the overexpression of TRPV1 channels decreased the viability of cancer cells." (PMID 28640864, 2017). "Based upon these interesting findings, further investigation should uncover roles of TRPV1 in cancer and identify other cannabinoid agonists that decrease cancer growth by targeting this pathway." (PMID 29066974, 2017). "TRPV1 activation, sensitization, and modulation have been indicated in many diseases, including irritable bowel syndrome, cancer, and diabetes." (PMID 29035314, 2017). "TRPV1 is among major pH sensors expressed in cancer cells, which belongs to an acid-sensitive ion channel." (PMID 27626482, 2016).